NES (nestin)
Diseases named in the same sentence as NES in open-access papers (continued):
Sharing a sentence is not in itself a finding about the gene and the disease.
glioma (continued). "There are a variety of markers used to isolate glioma stem cells, CD133 and Nestin are the most commonly used two markers that are widely expressed in various tumor cells, such as malignant glioma, liver cancer, ovarian cancer, colon cancer, lung cancer, etc.." (PMID 25967234, 2015). "This study used Meta-analysis method to systematically evaluate the literatures on the relationship between the expression of Nestin, CD133 that were multiple markers involving glioma stem cells and the prognosis of patients with glioma." (PMID 25967234, 2015). "Nestin (NES, blue module) is a stem cell marker that regulates the migration, invasion and growth of human gliomas." (PMID 25940437, 2015). "Recently, the markers of glioma stem cell that are studied more than others include CD133, nestin, HMGA1, A2B5, etc.." (PMID 25967234, 2015). "By the end of the review 13 literatures on glioma (9 CD133 and 6 nestin; 1,490 patients), meeting our inclusion criteria for meta-analysis, were left with sufficient data for extraction." (PMID 25967234, 2015). "In the case of oncolytic HSV rQNestin34.5, treatment with 5-AZA was sufficient to de-repress transcription under control of the Nestin promoter, allowing viral gene expression, increased viral replication, and HSV-mediated glioma cell killing." (PMID 25101247, 2014). "In this study, we assessed the prognostic role of the isolation of glioma CSCs (gCSCs) and expression of stem cell markers (PDPN, CD133, and nestin)." (PMID 25580136, 2014). "Similar findings have been observed in patients with glioma in that neurosphere formation and the expression of stem cell markers, such as podoplanin (PDPN), CD133, and nestin, were found to be prognostic markers of clinical outcomes." (PMID 25580136, 2014). "In fact, Nestin and CD133 are generally regarded as markers of both neural stem cells and CSC, and characterize the pathological glioma stem cell niches." (PMID 25121761, 2014). "As Nestin cells are the targeted cell-of-origin for the BSG model used here, it is possible that Nestin+/Pax3+ progenitors give rise to Pax3-High glioma in this mouse model." (PMID 25330836, 2014). "The high (fifth) generation glioma implants were double-stained for GFAP and rat-specific nestin to evaluate the glial nature of the infiltrating host cells." (PMID 22539956, 2012). "To generate tumors that mimic the proneural subtype of glioma, we injected the RCAS-PDGF avian retrovirus into Ink4a/Arf heterozygous mice that express the RCAS receptor tv-a under the control of the Nestin promoter." (PMID 22393407, 2012). "Using the RCAS/TV-A system we established mouse glioma cell lines, derived from PDGFB induced tumors, in Ntv-a (the avian TVA receptor for RCAS virus driven by Nestin promoter) transgenic mice with wild type, Ink4A-/- or Arf-/- genetic backgrounds." (PMID 21733196, 2011). "The positive expression rates of Nestin (103/125, 82.4%) and CD133 (98/125, 78.4%) in patients with gliomas were higher than those in normal brain tissues (both 1/10, 10%) significantly (p < 0.001)." (PMID 19108713, 2008). "Immunohistochemical analysis with anti-Nestin and anti-CD133 antibodies revealed dense and spotty staining in the tumor cells and their expression levels became significantly higher as the glioma grade advanced (p < 0.05)." (PMID 19108713, 2008). "The aim of this study was to investigate the correlation of the stem cell markers Nestin and CD133 expression with the grading of gliomas, and to evaluate their prognostic value." (PMID 19108713, 2008). "The expression and location of Nestin and CD133 in the 125 patients of primary gliomas were examined using immunostaining analysis." (PMID 19108713, 2008).
glioma (continued). "With its disease specificity and response to treatment demonstrated in further analysis, Nestin and CD133 can be considered as markers of tumor burden and recurrence in human gliomas." (PMID 19108713, 2008). "However, we observed a significant increase in the expression of stemness and malignancy markers such as CD133, L1CAM, Casp3, Nestin, and CD44 in surviving cells of both primary glioma and relapse cultures." (PMID 41304780, 2025). "In GSLCs and glioma tissues, Sohlh1 expression was negatively correlated with the expression of GSLC markers, such as Nestin, CD133, CD44, SOX2 and OCT4, whereas Sohlh1 expression was positively correlated with the expression of GSLC differentiation markers, such as MAP2, GFAP and MBP." (PMID 40418209, 2025). "In addition, both DM-α-KG and SP promoted the differentiation of glioma cells through elevated GFAP expression and reduced Nestin, CD133, and CD44 expression, suggesting that α-KG accumulation can promote the differentiation of glioma cells." (PMID 39872214, 2024). "In vivo, glioma stem cells (GSCs) with tumor self-renewal ability and aggressive growth metastasis are typically found in the perivascular niche, expressing SOX2, OLIG2, and NESTIN." (PMID 38390494, 2024). "Notably, subsequent multiplex histologic studies demonstrated not only the predominant presence of Hsp70 in live glioma tissues but also its colocalization in tumor stem cells (as described by CD133, SOX2, and nestin stemness markers coexpression)." (PMID 39015084, 2024). "The findings provided do not support the predictive significance of Nestin expression in newly diagnosed GBM, despite the fascinating association between it and the histological grade of gliomas." (PMID 38925618, 2024). "Moreover, in the classical GBM subtype, a correlation was confirmed between the CREB5 gene and genes important for stemness of glioma stem cells, such as OLIG2 and NES." (PMID 38418476, 2024). "However, the upregulation of FGF2 and NES indicates the presence of an activated microglia phenotype, as these processes such as angiogenesis and cancer stem cell formation are primarily driven by glioma-associated microglia rather than their quiescent phenotype." (PMID 38317968, 2024). "Another study focused on the common features between glioma stem cells and NSC in the SVZ and summarized these features, which included nestin expression, high motility, proliferative potential, association with blood vessels, and bilateral communication with constituents of the niche." (PMID 36980563, 2023). "Furthermore, glioma stem cells have many similarities with SVZ NSCs, such as nestin expression, high motility, diversity of progeny, proliferative potential, association with blood vessels, and bilateral communication with constituents of the niche." (PMID 37655012, 2023). "In a recent study of temozolomide-resistant glioma cell colonies derived from a TMZ-exposed glioma cell line, the expression of stem cell markers such as CD133 and nestin was significantly higher in the newly formed tumor cells compared to their parent cells prior to TMZ exposure." (PMID 38275375, 2023). "The mouse model of high-grade glioma used, which displays characteristics of human GBM, was created through intracerebral injection of vector-infected chicken fibroblasts (DF-1) producing RCAS-PDGF-B virus into Nestin-tva, Ink4a-arf −/− transgenic mice." (PMID 35879332, 2022).
glioma (continued). "The degree of aggression quantified by Ki-67 is not relevant in the case of grade 4 gliomas, which was also supported by the reactivity to nestin." (PMID 36136867, 2022). "Undifferentiated (or de-differentiated) glioma stem cells are a unique subset of therapy-resistant cells that express markers of stemness, including CD133+ and neural stem cell markers like nanog, Sox2, and Nestin." (PMID 36316307, 2022). "In addition, stem cell markers, such as, SOX2 and Nestin, were also upregulated in GBM-RICCS compared with the control group, suggesting that GBM-RICCS exhibits stem-like characters in glioma cells." (PMID 34831193, 2021). "More importantly, we identified that collagen/FN stimulated glioma progression through integrin αvβ3-induced PI3K/AKT/SOX2 and CDC42/F-actin/YAP-1/Nupr1/Nestin double signal activation simultaneously, expounding the underlying mechanism of the extracellular matrix-induced tumor signaling network." (PMID 33408794, 2021). "Furthermore, we observe that ablation of HDAC1 function in GSCs suppressed expression of key glioma stemness markers like SRY-box transcription factor 2 (SOX2), Nestin, and oligodendrocyte transcription factor 2 (OLIG2)." (PMID 34494550, 2021). "In addition, we assessed the stemness of glioma cells by measuring a panel of stem cell marker genes using western blotting analysis and observed significantly reduced expression levels of CD133, Nestin, Nanog, and SOX-2 after curcumol treatment." (PMID 34739394, 2021). "Our in vitro results demonstrated that 3D collagen/FN culture could induce the PI3K/AKT and CDC42/YAP/NUPR1 signal activation in glioma cells, resulting in growth factors SOX2/Nestin up-regulation." (PMID 33408794, 2021). "However, knockdown of PIM1 by siRNA revealed a strong reduction of the two most widely accepted glioma stem cell markers, CD133 and Nestin." (PMID 34681783, 2021). "On the other hand, genetic knockout of ATM in human glioma cells showed significantly less expression of CD133, Oct4, Nestin, and activated STAT3, four important markers of glioma CSCs, suggesting that ATM activation were directly responsible for glioma CSC maintenance." (PMID 32566127, 2020). "Specimens from seven glioma cases were analyzed by immunohistochemical staining for CD34, lymphatic endothelial hyaluronic acid receptor 1 (LYVE‐1), prospero‐related homeobox 1 (Prox1), nestin, and hypoxia‐inducible factor 1α (HIF‐1α)." (PMID 31960509, 2020). "In fact, TAT-Cx43266–283 importantly reduced not only the number of human glioma cells, but also their expression of nestin, suggesting that the remaining glioma cells did not exhibit stem cell properties known to drive recurrence." (PMID 31883012, 2020). "Immune checkpoint molecules, such as PD-1/PD-L1 and, a marker of glioma stem cell-like phenotype, such as nestin did not change either after vaccination." (PMID 32164575, 2020). "Glioma cells may express the intermediate filaments vimentin, GFAP, nestin, synemin, and α-internexin." (PMID 31003495, 2019). "As opposed to healthy glia cells, glioma generally possess increased amounts of the intermediate filaments vimentin, nestin, and GFAP." (PMID 31003495, 2019). "Univariate and multivariate analysis of biomarker expression in the treatment-naïve glioma cohort showed significantly lower values for vimentin (p = 0.0002), VEGFR2 (p = 0.0002), nestin (p = 0.003), Ki67 (p = 0.006) and HLA1 (p = 0.008) proteins in IDHmt vs wt tumors." (PMID 31881020, 2019). "Both in vivo and in vitro studies showed that hydrogen treatment could attenuate the stemness of glioma cells, which was evidenced by the decreased expression of stemness markers (CD133 and Nestin) and the enhanced expression of glia marker GFAP." (PMID 31113492, 2019).
glioma (continued). "Long-term exposure of glioma cell lines containing small stem cell populations to therapeutic stress (temozolomide) conferred differentiated glioma cells with stemness and pluripotency markers, such as CD133, SOX2, Oct4 and Nestin, whilst also upregulating HIF1/2α expression." (PMID 30510501, 2018). "Moreover, glioma stem cell division showed asymmetry in the distribution pattern of other key stem cell markers, such as Numb, EGFR and Nestin." (PMID 30510501, 2018). "The differentiated cells diminished expression of nestin, CD133 (prominin-1), and A2B5 putative glioma stem-cell markers, attenuated growth, diminished expression of ligands for activating NK cell receptors, while upregulating class I HLA ligands for NK cell inhibitory receptors." (PMID 29967607, 2018). "Therefore, nestin, ABCG2 and CXCR4 are included as the phenotype markers for identifying glioma stem cells." (PMID 28615716, 2017). "Additionally, the glioma stem cell-like markers CD133 and nestin were downregulated when hsa-miR-107 was overexpressed." (PMID 29136645, 2017). "The proliferation of CD133+ CSCs isolated from CSCs derived from the U251 and SF295 glioma cell lines and from human glioma samples was upregulated on a time- and concentration-dependent basis by LPS stimulation, with increases in CD133, NANOG, and NESTIN mRNA and protein levels." (PMID 28881826, 2017). "Interestingly, CUR was shown to both inhibit glioma cell proliferation and induce glioma cells to form spheres which were positive for CD133 and Nestin expression." (PMID 28611316, 2017). "Nestin has been connected to the stemness of GBM cells and to poor prognosis of glioma patients." (PMID 28069038, 2017). "Adult glioma stem cells share the expression of a panel of proteins physiologically present during early embryonic development of the central nervous system, such as CD133, Nestin, SOX-2 and other less well characterized marker proteins." (PMID 27213425, 2016). "Strikingly, overexpression of Oct4 in C6 cells was able to increase the expression of Nestin and Stat3 phosphorylation while decreasing the expression of GFAP, which suggests that Oct4 might inhibit the differentiation of glioma cells." (PMID 26381429, 2016). "On the other hand, Nestin high expression was associated with worse prognosis in terms of OS and PFS in patients with WHO II-III glioma but not WHO IV." (PMID 25967234, 2015). "Additionally, SHH activated CD133+ glioma cells demonstrated an increased expression pattern of stemness markers like CD133, SOX-2 and Nestin." (PMID 24978848, 2014). "Virally transduced expression of active Ras and Akt induces glioma formation from nestin-expressing neural progenitors but not from GFAP-expressing astrocytes in mice." (PMID 23424671, 2013). "The presence of a glioma implant induced proliferation of host nestin-positive cells in the ipsilateral, but not the contralateral SVZ." (PMID 22539956, 2012). "The Proneural subgroup of gliomas, which is characterized by increased PDGF signaling, can be effectively modeled using the RCAS/tv-a system of retroviral gene transfer of PDGF into Nestin-expressing cells in neonatal mouse brains." (PMID 22393407, 2012). "Glioma stem cells are characterized by self-renewal, limitless proliferation, tumor initiation, multi-potent differentiation and expression of stem cell surface markers such as CD133 and nestin." (PMID 23554660, 2010). "Therefore, the purpose of this study is to determine the correlation of Nestin and CD133 expression with the grading of gliomas and their predictive efficiency in clinical outcome of patients." (PMID 19108713, 2008). "Although the correlation of nestin expression and histologic grade in glioma is of considerable interest, the presented data does not support its prognostic value in newly diagnosed GBM." (PMID 18817556, 2008). "In conclusion, Nestin and CD133 expression may be a potential indicator of the biological aggressiveness of gliomas." (PMID 19108713, 2008).
glioma (continued). "Although the correlation of nestin expression and histologic grade in glioma is of considerable interest, the presented results do not support its influence on prognosis in GBM patients." (PMID 18817556, 2008). "In GBM, CD133+ and Nestin+ cells (representing GSCs) are located in close proximity to the tumor microvascular density (MVD), whereas a lower number of CD133- and Nestin- cells (representing differentiated glioma cells [DGCs]) are located in the vicinity of the blood vessels." (PMID 35642785, 2022). "Moreover, stem cell markers, such as, SOX2, and Nestin, were upregulated in RICCS, compared with Cont, suggesting that RICCS might exhibit stem-like characters in glioma cells." (PMID 34831193, 2021). "In addition, STAT3 binding to the Notch1 promoter inhibits this signaling pathway and may impede the maintenance of glioma stem-like cells while reducing the expression of glioma stem cell markers CD133, SOX2, and nestin." (PMID 34439159, 2021). "Also, PI3K/AKT inhibitors or Nestin suppression did not eliminate the colony formation or suppress glioma cell proliferation." (PMID 33408794, 2021). "In addition, CD133+ and Nestin+ glioma stem-like cells could also regulate SDF-1α and CXCR4, which subsequently promote leukocyte migration and glioma progression." (PMID 32725165, 2020). "In a glioma model, FASN expression and lipid synthesis were high in patient-derived TICs, along with glioma TIC markers SOX2, fatty acid binding protein-2 (FABP2) and nestin, and FASN inhibition led to downregulation of these markers as well as decreased viability and invasivity." (PMID 31661927, 2019). "Therefore, in this work, since the Notch-1 and OPN molecules are related to the maintenance of angiogenesis and GSLCs, we analyze the distribution of Notch-1 and OPN immunopositivity in relation to nestin and CD133 and the proangiogenic factor VEGF in early to advanced stages of ENU-gliomas." (PMID 30140373, 2018). "The transfected glioma cells grown in differentiated (DMEM with 10% FBS allows to maintain mixture of cells with various lineage) and stem cell conditions (NSA media supplemented with N2, B27, EGFFR and FGF) were stained using CD133, NESTIN, GFAP and OLIG2 markers." (PMID 27517625, 2017). "Our immunohistochemistry results for Nestin show less intermingling between tumor and non-tumor cells in NA-treated brain slices as compared with control, further confirming that NA inhibits the infiltration of C6 glioma cells into normal brain tissues." (PMID 28256591, 2017). "Interestingly, glioma spheroid cultures contain characteristics of GSLCs, and may express stem cell markers such as CD133, Nestin, Sox2 and SSEA-1." (PMID 28074274, 2017). "However, Ki-67 and Nestin expression did not significantly differ among the groups of GSCs, indicating that both groups exhibited similar mitotic activity and glioma stemness." (PMID 25992628, 2015). "Finally, using human malignant glioma stem cells (OB1 cell line), we showed that CTGF treatment induced GFAP, CD133, Nestin and inhibited Sox2 expression, suggesting a possible role for CTGF not only during normal brain development but also in the glioma differentiation program." (PMID 26241738, 2015). "Although our study suggests that β-catenin is not directly involved in the transcriptional regulation of nestin, wnt/β-catenin signalling could be involved in maintaining an undifferentiated, stem-like glioma cell phenotype." (PMID 22919349, 2012). "Large numbers of nestin-positive host cells were found at the immediate tumor border, whereas GFAP-positive host cells with typical astrocytic morphology were distributed loosely in a halo more distal to the zone containing mouse nestin-positive cells that surrounded the D566 human glioma implants." (PMID 22539956, 2012).